LEP (leptin)
Diseases named in the same sentence as LEP in open-access papers (continued):
Sharing a sentence is not in itself a finding about the gene and the disease.
gallstones (13 papers, 2014 to 2025). Solid crystalline precipitates in the biliary tract, usually formed in the gallbladder, resulting in the condition of cholelithiasis. "In vivo experiments have verified that prolonged intraperitoneal administration of high-dose leptin (10 μg/g per day) induces weight loss and cholesterol gallstone formation in C57BL/6 J ob/ob mice." (PMID 38883189, 2024). "In vivo experiments confirmed that long-term intraperitoneal administration of high doses of leptin (10 μ/g/d) induced weight loss in food-fed C57BL/6J ob/ob mice was associated with cholesterol gallstone formation." (PMID 37964952, 2023). "Obese leptin-deficient (ob-ob) mice have large gallbladder volumes with decreased contraction and are predisposed to gallstone formation, and administration of leptin to these mice causes weight loss and restores gallbladder function." (PMID 33167521, 2020). "Leptin was found to promote cholesterol crystallization and gallstone formation and, consistent with this finding, was reported to affect the components and secretion of bile in leptin-deficient mice." (PMID 33167521, 2020). "High leptin levels are strongly associated with cholesterol metabolism abnormalities, which can cause cholesterol supersaturation in bile and subsequently lead to cholesterol gallstone formation." (PMID 40745581, 2025). "Leptin promotes gallstones formation, which may be linked to decreased bile acid secretion via downregulation of the OB-Rb/AMPKα2/BSEP signaling pathway." (PMID 38238700, 2024). "Therefore, increased serum leptin can increase cholesterol secretion into bile, resulting in subsequent bile supersaturation with cholesterol and increased risk of gallstones." (PMID 37004051, 2023). "In obese individuals, adipocytes play a critical role by promoting cholesterol crystallization and gallstone formation through the secretion of leptin." (PMID 39944962, 2025). "A high serum leptin concentration reflects a high body fat percentage, which contributes to gallstones development." (PMID 38238700, 2024). "Third, leptin and adiponectin, secreted by fat cells, have an additional link with gallstone formation." (PMID 37004051, 2023). "Furthermore, in vitro experiments have demonstrated that leptin impacts gallstone formation by regulating bile acid metabolism." (PMID 38883189, 2024). "At the same time, by acting on the fibroblasts, leptin decreases the contraction function of the gallbladder wall, increases the volume of the gallbladder, and leads to the accumulation of cholestasis, eventually contributing to the formation of gallstones." (PMID 35346065, 2022). "Moreover, previous studies showed that leptin represents a key factor during gallstone formation, either directly or indirectly, by modulating gallbladder motility and regulating the expression of gallbladder genes related to the secretion and reabsorption of electrolytes and water." (PMID 29088261, 2017). "Previous research reported that leptin-deficient or leptin-resistant obese mice exhibited decreased gallbladder responses to NPY and CCK compared with control mice with normal leptin metabolism, suggesting that leptin dysregulation is associated with gallbladder motility and gallstone formation." (PMID 29088261, 2017). "In addition, recent studies showed that leptin and some metabolic kinase signalings, such as LKB1-AMPK and -SIK3 could regulate bile acid metabolism and might affect gallstone formation." (PMID 24598574, 2014).
liver cirrhosis (13 papers, 2010 to 2025). "Adiponectin, leptin and visfatin associated significantly with liver cirrhosis in HCV patients (P<0.01)." (PMID 32212784, 2020). "Discordant findings on leptin levels in liver cirrhosis patients indicate that this adipokine is closely linked to BMI and nutritional state rather than hepatic function." (PMID 28661458, 2017). "There are references in other types of liver cirrhosis about leptin, in which this hormone has been demonstrated to be in both high and low levels." (PMID 34209386, 2021). "Patients with liver cirrhosis show increased serum leptin levels, particularly when expressed in unit fat mass, with a 2-fold increase in fasting levels compared with healthy individuals." (PMID 32731496, 2020). "This study was conducted to assess between LEPR Gln223Arg and serum LEP level in Egyptian patients with liver cirrhosis that leads to HCC and to clarify its relationship with the clinical-pathological characteristics of patients with HCC." (PMID 33369452, 2020). "It has been reported that serum leptin level is increased significantly in human patients with liver cirrhosis and HCC." (PMID 30718259, 2019). "This suggests that anthropometric variables and nutritional status are closely associated with serum leptin and have to be considered when analyzing systemic leptin levels in patients with liver cirrhosis." (PMID 28661458, 2017). "Systemic leptin is higher in healthy females, and this also applies for patients with liver cirrhosis." (PMID 28661458, 2017). "Accordingly, plasma leptin concentration is higher in the radial artery than the portal vein in very obese subjects and in patients with liver cirrhosis." (PMID 28661458, 2017). "Subcutaneous adipose tissue is the major source of serum leptin, and this seems to also apply for patients with liver cirrhosis." (PMID 28661458, 2017). "Several studies report that leptin is increased in patients with liver cirrhosis." (PMID 28661458, 2017). "Systemic leptin positively correlates with BMI in patients with liver cirrhosis." (PMID 28661458, 2017). "Though patients with liver cirrhosis and ascites have higher IL-6 and IL-8 in serum than those without ascites, serum leptin is unchanged." (PMID 28661458, 2017). "Thus, it is not clear whether leptin is further changed in liver cirrhosis when compared to non-cirrhotic patients with chronic liver diseases." (PMID 28661458, 2017).
renal cell carcinoma (13 papers, 2011 to 2025). "Background and Objectives: To investigate the clinical significance of adipokines’ [leptin, leptin receptor (leptin-R), adiponectin, and resistin] expression on the characteristics and survival outcomes of patients with renal cell carcinoma (RCC)." (PMID 41010935, 2025). "Analyses of transcriptomic data and patients’ clinical information have revealed leptin’s prognostic significance in renal cell carcinoma (RCC)." (PMID 33804101, 2021). "Previous studies showed that leptin promoted viability and metastasis of renal cell carcinoma cells via activating the ERK1/2 and JAK/STAT3 signaling which could be partially abolished by ERK phosphorylation inhibitor U0126 and STAT3 phosphorylation inhibitor AG490, respectively." (PMID 27185268, 2016). "In addition, the PRAT browning process has been specifically detected in renal cell carcinoma (RCC), being characterized by upregulated expression of brown/beige adipocytes markers (UCP1, PPAR-ɣ, c/EBPα, and PGC1α) and downregulated white fat cells markers, such as LEPTIN, SHOX2, HOXC8, and HOXC9." (PMID 40227577, 2025).
thyroid (13 papers, 2011 to 2023). "The molecular mechanism underlying leptin effects was investigated by focusing on the two main oncogenic pathways activated in thyroid tumorigenesis through the measurement of phospho-ERK and phospho-AKT expressions." (PMID 30906321, 2019). "Of the three adipokines, leptin presents as an interesting diagnostic option for thyroid malignancy; leptin has a 100% accuracy, as well as high sensitivity and specificity." (PMID 25810718, 2015). "Postpartum thyroiditis patients are associated with significantly elevated leptin levels, and there may be an association between the two." (PMID 36339447, 2022). "An association between thyroid function and BMI may be attributable to alterations in energy expenditure or leptin produced by adipocyte tissue, although the mechanism is unclear." (PMID 26151950, 2016). "We believe that Allo-aca can alter the differentiation of Treg/Th17 cells by inhibiting the leptin signaling pathway, thereby alleviating thyroid injury in EAT mice." (PMID 36339447, 2022). "Furthermore, it has been reported that leptin has direct effects on the formation of thyroid disorders." (PMID 37152970, 2023). "It has been recognized that there is a narrow relationship between thyroid disease and T2DM, in which the following observable facts are underlying: homeostasis disorder of hepatic glycaemia and interaction with adipokines like adiponectin and leptin." (PMID 30151097, 2018). "There are many studies investigating circulating leptin levels in thyroid disorders." (PMID 27193069, 2016). "However, increased leptin level in postpartum thyroiditis has been reported." (PMID 22007338, 2011). "In the nonnodular thyroid group, thyroid volume was also positively related to serum insulin and HOMA-IR, whereas a negative correlation between thyroid volume and leptin was identified in the nodular thyroid group." (PMID 28356911, 2017). "In the nonnodular thyroid group, thyroid volume was also positively related to serum insulin levels and HOMA-IR, whereas a negative correlation between thyroid volume and levels of leptin was identified in the nodular thyroid group." (PMID 28356911, 2017). "Although leptin was differentially expressed among thyroid lesions, it did not correlate with any clinicopathological feature." (PMID 25810718, 2015).
Bardet-Biedl syndrome (12 papers, 2012 to 2025). A ciliopathy with multisystem involvement. "Mean scores of our AS population are approximately 2 points below the mean scores of PWS, Bardet Biedl Syndrome, and Alström Syndrome, and they are 6–7 points below the mean of children with defects in the leptin–melanocortin pathway, regulating hunger and satiety (Table A3 in the Appendix A)." (PMID 37762921, 2023). "Congenital disorder of HO mainly includes abnormalities in the leptin‐melanocortin pathway, leading to monogenic obesity syndrome, such as Prada–Willi syndrome (PWS), melanocortin‐4 receptor (MC4R) defect, leptin or proopiomelanocortin (POMC) deficiency, and Bardet–Biedl syndrome." (PMID 39661011, 2025).
brain tumors (12 papers, 2011 to 2025). "Correlation analysis showed an inverse relationship between CPET results and leptin, emphasizing the role of radiotherapy as a possible cause in the genesis of a greater cardiovascular risk in survivors of childhood brain tumors." (PMID 38254811, 2024). "Leptin/ObR are present in a broad range of brain tumors, with the level of expression associated with the degree of malignancy, raising the possibility that phenotyping of peripheral circulating leptin/ObR may be a useful strategy for predicting tumor grade." (PMID 33316976, 2020). "Leptin is a pleiotropic hormone whose mitogenic and angiogenic activity has been implicated in the development and progression of several malignancies, including brain tumors." (PMID 21771332, 2011). "It was demonstrated that, in CCS of brain tumors, plasma leptin values were higher than in healthy subjects and correlated with central fat indicators such as waist-to-height ratio and waist-to-hip ratio." (PMID 38254811, 2024). "Some authors suggest that metabolism-regulating hormones as leptin and B-lipotropin are directly produced by brain tumors, leading to decrease in subcutaneous fat and excess high release." (PMID 35978327, 2022). "Leptin and its receptor were reported to be highly expressed in brain tumors, and the patients with the tissues displaying those biomarkers associated with the degree of malignancy." (PMID 33799880, 2021). "To date, most of the findings in clinical studies remain preliminary and of heterogenous character, although experimental studies have underpinned the relevance of leptin and ObR in the pathophysiology of brain tumors in general." (PMID 33316976, 2020). "Using immunohistochemistry and real-time PCR, leptin/ObR expression was found in 55% and 61%, of 87 human brain tumor biopsies." (PMID 33316976, 2020). "In parallel, further experimental studies are needed to elucidate the precise mechanism of action of the leptin/ObR system in the context of different brain tumor pathologies and grades." (PMID 33316976, 2020). "We previously demonstrated that the expression of leptin and ObR in human brain tumor tissues correlates with the degree of malignancy, and the highest levels of both markers are detected in GBM." (PMID 21771332, 2011). "Because leptin and ObR in human brain tumors are commonly coexpressed, leptin effects are likely to be mediated by autocrine pathways." (PMID 21771332, 2011). "We recently demonstrated that both leptin and ObR proteins are overexpressed in human brain tumors relative to normal brain tissue, and that leptin/ObR expression levels positively correlate with the degree of malignancy." (PMID 21771332, 2011). "The roles of the leptin-leptin receptor signaling axis in brain tumor progression were evaluated." (PMID 33799880, 2021). "In particular, data from experimental (in vivo and in vitro) and human studies indicate that the leptin/ObR axis and its degree of expression may differ depending on brain tumor grade." (PMID 33316976, 2020). "In addition, leptin and its receptor have been shown to be expressed in various brain tumor pathologies." (PMID 33316976, 2020). "Radiation, as treatment of brain tumors, may also directly damage hunger and satiety centers, as well as reduce their sensitivity to leptin." (PMID 31847472, 2019). "Leptin has been shown to potentiate angiogenesis, cell migration, cell survival, and invasion, and inhibit apoptosis in cell lines; these characteristics are yet to be proven in human tumor tissue samples, especially in brain tumors." (PMID 30803210, 2019). "New evidence suggests leptin can be involved in the development of brain tumors." (PMID 21771332, 2011). "We focussed on leptin and sPLA2-IIA, alone or combined, in the search for factors and mechanisms involved in the invasive behaviour of brain tumors." (PMID 28249041, 2017).
hyperprolactinemia (12 papers, 2014 to 2025). Abnormally high level of prolactin in the blood. "Hyperprolactinemia occurs during gestation and lactation with marked hyperphagia associated with leptin resistance." (PMID 24667351, 2014). "The contrasting results in regard to social groups on hyperprolactinemia and leptin highlight the complexity of social variables on hormone levels, and certainly warrant further investigation." (PMID 29186207, 2017). "The relation between leptin levels and hyperprolactinemia is inconclusive." (PMID 38370355, 2024). "Potential mechanisms in which hyperprolactinemia may induce weight gain include decreased dopaminergic tone and leptin resistance." (PMID 38370355, 2024). "Indeed, our patient presented with a clinical history of oligo-menorrhea and showed almost undetectable gonadotropin levels, probably determined by the combination of reduced leptin levels and iatrogenic hyperprolactinemia." (PMID 32117065, 2020). "In addition, the antagonism of 5HT2c, H1 receptor, hyperprolactinemia, and increase in the serum leptin level consequence in weight gain in patients taking antipsychotic medications." (PMID 33294450, 2020). "In high-producing breeds, hyperprolactinemia may prioritize milk synthesis over metabolic recovery, while in Simmental cows, lower PRL signaling likely allows a more harmonized regulation of lipogenesis, lipolysis, and leptin expression." (PMID 41373870, 2025).
Zinc deficiency (12 papers, 2006 to 2024). A deficiency of the essential metal Zinc; an essential cofactor for many enzymes. "A zinc deficiency will also increase leptin production, increasing the inflammatory changes found with excess adiposity." (PMID 39062266, 2024). "For example, some studies (in animals) have shown that zinc deficiency is associated with a significant increase in leptin levels." (PMID 39337701, 2024). "Thus, in non-obese individuals, zinc provides a regulatory signal for food intake via leptin that can explain the decreased appetite and anorexia observed in zinc deficiency (105,145." (PMID 38260166, 2023). "Interestingly, in healthy humans and rodents, dietary zinc deficiency decreased circulating leptin levels, whereas zinc supplementation increased leptin levels proportionally to zinc adjustments." (PMID 38260166, 2023). "Vitamin A (retinoic acid)-deficient mice had higher leptin mRNA expression, but zinc deficiency reduced leptin gene expression and secretion in rat adipocytes, suggesting that the effect of micronutrients on leptin and other adipokines still needs to be explored." (PMID 35548560, 2022). "The present study investigated whether zinc deficiency induces leptin secretion by activating a JAK2/STAT3 signaling pathway and leads to osteoblastic apoptosis." (PMID 36615735, 2022). "Some studies have found that zinc may be the medium of leptin synthesis, and zinc deficiency can reduce the secretion of leptin." (PMID 35565860, 2022). "In addition, Ott and Shay also reported that zinc deficiency reduced the expression and secretion of leptin in cultured rat adipocytes, which was similar to the findings of our study." (PMID 29057818, 2017). "However, it is also reported in some studies that short-term zinc supplementation reduces serum leptin level, whereas zinc deficiency for three weeks increases circulatory leptin level." (PMID 29057818, 2017). "However, dietary zinc deficiency worsened ethanol-induced decline of plasma leptin level, which may contribute to the detrimental effect of zinc deficiency on ethanol-impaired hepatic fatty acid oxidation." (PMID 24155903, 2013). "Therefore, zinc deficiency may directly contribute to the inflammatory state of adipose tissue in obese individuals, and it may also affect the amount of leptin produced and released by this tissue which ultimately has a proinflammatory effect itself and promotes the secretion of other cytokines." (PMID 38260166, 2023). "Dietary zinc deficiency exaggerated ethanol-induced reduction of plasma leptin, although it did not further worsen ethanol-induced WAT mass reduction." (PMID 24155903, 2013). "Dietary zinc deficiency exaggerated ethanol-induced reduction of plasma leptin, although it did not affect ethanol-induced reduction of white adipose tissue mass." (PMID 24155903, 2013). "Zinc deficiency could contribute to leptin insensitivity in non-adipose tissues such as liver and muscle through loss of the inhibitory effect of zinc on PTP1B." (PMID 38260166, 2023). "Finally, zinc deficiency induces acute hypoleptinemia, however oral zinc supplementation did not affect Ache male leptin levels." (PMID 16942616, 2006).